CYP19A1 (cytochrome P450 family 19 subfamily A member 1)
Diseases named in the same sentence as CYP19A1 in open-access papers (continued):
Sharing a sentence is not in itself a finding about the gene and the disease.
colon cancer (continued). "Inhibition of CYP19A1 resulted in the downregulation of PD-L1, IL-6 and TGF-β expression in colon cancer cells, thereby enhancing the tumor-killing ability of CD8+ T cells." (PMID 41415563, 2025). "The results showed that the expression levels of ACSL6, CYP19A1, LRP2, OSBPL3 and SLCO1A2 were considerably increased, while those of ACOX1, FABP4, PLAAT5, PPARGC1A and TNFAIP8L3 were decreased in colon cancer." (PMID 38045683, 2023). "Secondly, we studied the expression and pathophysiological significance of CYP19A1 in vitro and in vivo, and further studies are needed on other LMGs including FABP4, LRP2, SLCO1A2, PPARGC1A and ALOXE3 in colon cancer." (PMID 37055842, 2023). "We found that CYP19A1 expression level was significantly positively correlated with PD-L1, IL-6 and TGF-β levels in the TCGA colon cancer dataset." (PMID 37055842, 2023). "Next, we further explored the possibility of using CYP19A1 as a target for sensitizing anti-PD-1 therapy, and found that the CYP19A1 inhibitor letrozole sensitized anti-PD-1 therapy in subcutaneous tumors derived from the MC38 and CT26 murine colon cancer." (PMID 37055842, 2023). "Collectively, we screened the six LMGs including CYP19A1, FABP4, LRP2, SLCO1A2, PPARGC1A and ALOXE3, and constructed a signature to predict prognosis and immunotherapeutic response in colon cancer, which was extendedly and externally validated." (PMID 37055842, 2023). "Knockdown of CYP19A1 by specific siRNA significantly impeded growth of orthotopic and subcutaneous MC38 colon cancer, but its combination with anti-PD-1 treatment was far more effective than monotherapy." (PMID 37055842, 2023). "Second, we uncovered for the first time that CYP19A1 inhibition downregulated PD-L1, IL-6 and TGF-β expression in colon cancer cells, and thereby enhanced the tumor-killing ability of CD8+ T cells." (PMID 37055842, 2023). "LPS also increased COX2, CXCL1, ELK1, ICAM1, TNFSF10 and ZFAND5 but decreased BCL2L1, CYP19A1 and E2F1 mRNA levels in the colon cancer cells." (PMID 37705049, 2023). "Here we integrated CYP19A1, FABP4, LRP2, SLCO1A2, PPARGC1A and ALOXE3 with clinicopathological information of patients to construct a prognostic nomogram in colon cancer." (PMID 37055842, 2023). "We discovered that CYP19A1 inhibition by letrozole or si-CYP19A1 downregulated GPR30, p-Akt and PD-L1 in HCT116 and HT29 colon cancer cells, which were greatly enhanced by exogenous addition of estradiol." (PMID 37055842, 2023). "CYP19A1 protein expression in the colon cancer tissues was negatively correlated with overall survival, and positively associated with N stage, and an independent prognostic parameter of overall survival." (PMID 37055842, 2023). "CYP19A1 knockdown boosted tumor-infiltrating CD8+ T cells and enhanced GzmB and IFNγ production, indicative of CD8+ T cells-elicited adaptive immunity against colon cancer, which were amplyfied in combination therapy." (PMID 37055842, 2023). "CYP19A1 inhibition by letrozole or siRNA strengthened the anti-tumor immune response of CD8+ T cells, induced normalization of tumor blood vessels, and enhanced the efficacy of anti-PD-1 therapy in orthotopic and subcutaneous mouse colon cancer models." (PMID 37055842, 2023).
lung carcinoma (7 papers, 2016 to 2024). "The correlation between CYP19A1 polymorphisms and lung cancer risk in the different groups (tumor type, LNM, and stage) was assessed." (PMID 36527059, 2022). "CYP19A1 gene polymorphisms, including rs727479 and rs3764221, have also been associated with an increased risk of lung cancer in small case-control studies." (PMID 34601599, 2022). "This study has identified revealed that the three SNPs (rs28757157, rs3751592, and rs59429575) of CYP19A1 are associated with lung cancer in the Chinese Han population." (PMID 36527059, 2022). "The aim of this study was to assess the association of CYP19A1 genetic polymorphisms with the risk of lung cancer in the Chinese Han population." (PMID 36527059, 2022). "At the same time, many works of literature have reported an inseparable relationship between the genetic variant of CYP19A1 and lung-related diseases, including lung cancer." (PMID 36527059, 2022). "Since the statistical significance of the correlation between CYP19A1 gene polymorphisms and the risk of lung cancer is slightly weak, further experimental studies are needed to verify the results of this study." (PMID 36527059, 2022). "In this study, the association of four SNPs in the CYP19A1 gene with the susceptibility to lung cancer in the Chinese Han cohort was assessed." (PMID 36527059, 2022). "In summary, our study defined SNPs of CYP19A1 (rs28757157, rs3751592, and rs59429575), which were significantly associated with lung cancer susceptibility." (PMID 36527059, 2022). "Previous reports have confirmed that aromatase had biological activity in lung cancer cells, and the polymorphisms of CYP19A1 may be related to the increased risk of lung cancer." (PMID 36339610, 2022). "It is clear that CYP19A1 polymorphism may cause changes in estrogen levels around the lungs, which in turn can affect the susceptibility of lung cancer." (PMID 36527059, 2022). "Subsequently, due to the lack of adequate information on factors such as dietary habits, occupational exposure, and air pollution, this study failed to assess the impact of these factors on the association between CYP19A1 variants and lung cancer susceptibility." (PMID 36527059, 2022). "Furthermore, the correlation between CYP19A1 polymorphisms and lung cancer risk in different groups (tumor type, LNM, and stage) was further assessed." (PMID 36527059, 2022). "CYP19A1 rs28757157 might contribute to an increased risk of lung cancer (p = 0.025, OR = 1.30, 95% CI 1.03–1.64)." (PMID 36527059, 2022). "Moreover, CYP19A1 rs727479 is also significantly associated with the incidence of lung cancer." (PMID 36527059, 2022). "That is, our study identified that SCD1 drives lung cancer metastasis by promoting CYP19A1 expression and estrogen production for the first time." (PMID 37047797, 2023). "Several cytokines, such as interleukin-6 (IL-6), oncostatin M, and tumor necrosis factor-α (TNFα), induce CYP19A1 gene expression in lung cancer through the regulation of estrogen synthesis." (PMID 37047797, 2023). "In order to verify the results of this study, it is necessary to clarify the relationship between the CYP19A1 gene and lung cancer through subsequent functional studies." (PMID 36527059, 2022). "Statistical and bioinformatics results highlighted the important roles of rs28757157, rs3751592, and rs59429575 in the outset of lung cancer in the total or stratified population, which helped improve our understanding of CYP19A1 in this disease." (PMID 36527059, 2022). "This suggests that CYP19A1 genetic variations may indirectly affect the occurrence of lung cancer, but the exact mechanism is unclear." (PMID 36527059, 2022). "Furthermore, we explored whether SCD1 promotes the invasion and migration of lung cancer cell lines by upregulating CYP19A1 and estrogen biosynthesis." (PMID 37047797, 2023).
lung carcinoma (continued). "However, there are still a large number of single-nucleotide polymorphisms (SNPs) in CYP19A1 whose association with lung cancer risk has not been reported." (PMID 36527059, 2022). "A total of 83 potential targets of ROB in lung cancer were collected and further screened by using Cytoscape software, and 7 targets of PTGS2, CYP19A1, PTGS1, AR, CYP17A1, PTGES and SRD5A1 were obtained as hub genes and 7 hub targets had good binding energy with ROB." (PMID 39450260, 2024). "There is a lack of sufficient research on local CYP19A1 expression and estrogen production in lung cancer." (PMID 37047797, 2023). "The hub targets of ROB action in lung cancer were further analyzed by combining 14 targets from Degree≥6, 10 targets each from MCC and MNC algorithms, and finally 7 common targets such as PTGS2, CYP19A1, PTGS1, AR, CYP17A1, PTGES and SRD5A1 were obtained from the final screening." (PMID 39450260, 2024).
aromatase deficiency (6 papers, 2016 to 2024). Aromatase deficiency disrupts the synthesis of estradiol, resulting in hirsutism of mothers during gestation of an affected child; pseudohermaphroditism and virilization in women; and tall stature, osteoporosis and obesity in men. "Aromatase deficiency is caused by biallelic pathogenic/likely pathogenic variants in the CYP19A1 gene (MIM*107910)." (PMID 38812815, 2024). "Variants in the CYP19A1 gene cause aromatase deficiency and are considered a rare recessive disease with about 40 cases of aromatase deficiency reported." (PMID 35432193, 2022). "In conclusion, the case reported here presented with ambiguous genitalia and exisiting aromatase deficiency, findings which were due to a novel mutation in the CYP19A1 gene." (PMID 29553041, 2018). "In patients with aromatase deficiency, more than 30 distinct mutations have been identified in the CYP19A1 gene, including missense, nonsense, small deletions and insertions, splice-site mutations, and one large intragenic deletion." (PMID 29553041, 2018). "Aromatase deficiency is a rare disease caused by CYP19A1 gene mutation and characterized by a decrease in estrogen synthesis." (PMID 29553041, 2018). "Here, we report the clinical and genetic features of three cousins with a novel homozygous mutation (568insC) in CYP19A1 that caused severe aromatase deficiency." (PMID 27086564, 2016). "A novel 568C insertion mutation in CYP19A1 can lead to severe aromatase deficiency." (PMID 27086564, 2016).
ovarian cancer (6 papers, 2017 to 2024). A primary or metastatic malignant neoplasm involving the ovary. "In cancer, particularly in hormone-dependent tumors such as breast and ovarian cancers, CYP19A1 is implicated in tumor progression through its role in estrogen biosynthesis, positioning it as a potential biomarker." (PMID 39457539, 2024). "Recently, the rs10046 (CYP19A1) variant was found to be associated with an increased risk of developing ovarian cancer." (PMID 38001897, 2023). "Rs727479 and a correlated SNP (rs749292) in the CYP19A1 gene region have also been reported to be associated with an increased risk of ovarian cancer in a small case-control study (367 cases and 602 controls) from Hawaii." (PMID 34601599, 2022). "Herein, we describe the disruptive functions of several miRNAs and lncRNAs seen in dysregulated cancer metabolism, with a focus on the gene encoding for aromatase (CYP19A1 gene) and estrogen synthesis as a novel therapeutic approach for treating ER-positive breast and ovarian cancers." (PMID 33920789, 2021). "Therefore, as a consequence of inhibition of STS, the low expression levels of CYP19A1 in endometrial and ovarian cancers might be up-regulated as well." (PMID 28674494, 2017).
preeclampsia (6 papers, 2018 to 2025). Preeclampsia is a hypertensive disorder of pregnancy that is characterized by new-onset hypertension with proteinuria presenting after 20 weeks of gestation, and depending on mild or severe forms may initially present with severe headache, visual disturbances, and hyperreflexia. "Notably, the testosterone-to-estradiol ratio, which indicates altered availability and/or function of CYP19A1-encoded aromatase was significantly different between women with preeclampsia and controls in our study." (PMID 39684415, 2024). "Studies have reported that corticotropin releasing hormone (CRH), PSG1 and CYP19A1 are directly related to the development preeclampsia." (PMID 33890634, 2021). "Placental CYP19A1 expression and function are diminished in pregnancies complicated by preeclampsia compared to controls." (PMID 30258364, 2018). "As shown in the disordered expression of C1QBP and CYP19A1 in PE tissues, the dysregulation of this novel signaling pathway may potentially contribute to the pathogenesis of preeclampsia by interfering with the normal induction of trophoblast differentiation." (PMID 40589522, 2025). "We identified CYP17A1, HSD17B3, SRD5A1, CYP19A1, CYP11B1, HSD11B1 and HSD11B2 as potentially affected enzymes in preeclampsia." (PMID 39684415, 2024).
Anxiety (5 papers, 2019 to 2025). Intense feelings of nervousness, tension, or panic often arise in response to interpersonal stresses. "Interestingly, prenatal BPA exposure downregulated the mRNA levels of Cyp19a1 in the brain of male offspring, whereas Cyp19a1 mRNA was increased in the female brain, with increased anxiety-like behavior and decreased exploratory behavior observed in both male and female F1 rats." (PMID 35220427, 2022).
Hypertension (5 papers, 2015 to 2025). The presence of chronic increased pressure in the systemic arterial system. "The rs10046 polymorphism of CYP19A1 gene and its probable association with cardiovascular system have been investigated in two studies, where the association of genetic changes of CYP19A1 gene with the occurrence of hypertension was investigated." (PMID 25861479, 2015). "In cardiovascular system, the rs10046 polymorphism of CYP19A1 gene has been investigated in two studies on the occurrence of hypertension." (PMID 25861479, 2015). "If confirmed in future studies, these results suggest that some CYP19A1 variants may have a protective effect and some may increase vulnerability to hypertension based on exposure to UT-Other and sex." (PMID 28002425, 2016). "CYP19A1 polymorphism -81371 C>T significantly interacted with sex to predict primary endpoints death, nonfatal MI, and nonfatal stroke among 568 acute coronary syndrome patients and 619 subjects from a randomized, controlled trial of hypertension followed for 3 years." (PMID 27187494, 2016). "The TT genotype of the CYP19A1 polymorphism encoding the aromatase enzyme involved in the final step of estrogen synthesis showed, namely, interaction with narrow waist girth for hypertension only in men, independent of age and BMI." (PMID 27680100, 2016). "The rs10046 polymorphism of CYP19A1 gene has been investigated in two studies on the occurrence of hypertension, but there are no studies on its correlation with coronary artery disease (CAD)." (PMID 25861479, 2015).
COVID-19 (4 papers, 2022 to 2024). A disease caused by infection with severe acute respiratory syndrome coronavirus 2. "Associations of serum E2 levels instrumented by rs7173595 in the CYP19A1 gene region with COVID-19 outcomes." (PMID 36250974, 2022). "In particular, the effect of reducing the expression of CYP19A1 by KSB191 may be expanded to apply to phytomedicine for lung diseases such as COVID-19 in men." (PMID 39683564, 2024).
hepatocellular carcinoma (4 papers, 2008 to 2021). A malignant tumor that arises from hepatocytes. "Upregulation of GPX4, PRDX1 and CYP19A1 genes have been previously detected in biopsies of HCV infected chimpanzees or in human hepatocellular carcinoma (HCC) samples." (PMID 18793431, 2008).
hypogonadism (4 papers, 2013 to 2025). A disorder characterized by decreased function of the gonads. "This extragonadal aromatization, catalyzed by the enzyme aromatase (CYP19A1), converts androgens to estrogens and represents a significant source of circulating estrogens in males, postmenopausal women and individuals with hypogonadism." (PMID 41155243, 2025).
Lipedema (4 papers, 2022 to 2026). Disorder of adipose tissue characterized by symmetric and bilateral enlargement of the lower extremities due to abnormal deposition of subcutaneous fat often in obese women. "Gene-expression analysis showed a higher expression of aromatase (CYP19A1)—responsible for the conversion of androgens to estrogen—in lipedema tAT compared to lean healthy control tAT and the abdominal AT of the same lipedema patient." (PMID 36551837, 2022). "CYP19A1 shows a significant upregulation in lipedema thigh AT compared to control thigh AT (p = 0.048)." (PMID 35625899, 2022). "Of note, CYP19A1 mRNA levels are significantly upregulated in lipedema thigh, compared to lipedema abdominal AT (p = 0.022) of the same individuals." (PMID 35625899, 2022). "Furthermore, gene expression studies show increased aromatase CYP19A1 ‒ the enzyme that converts androgens to estrogen ‒ in lipedema subcutaneous fat compared to healthy controls and even to the abdominal fat of the same patient." (PMID 41512532, 2026). "E2 treatment also significantly increased the gene expression of CYP19A1 (~10-fold) in HD-treated healthy ASCs; however, it did not affect lipedema cells." (PMID 38791004, 2024). "CYP19A1 and LIPE gene expressions were significantly increased in estrogen-treated healthy ASCs and spheroids, respectively, while estrogen upregulated the expression of PPAR-Υ2 and ERα in estrogen-treated lipedema-differentiated adipocytes and spheroids." (PMID 38791004, 2024). "Furthermore, estrogen treatment increased the expression of aromatase gene CYP19A1, an enzyme that converts androgens to estradiol, in healthy ASCs but not in lipedema." (PMID 38791004, 2024). "Interestingly, cultured ASC P2 showed the highest CYP19A1 expression compared to the other samples analyzed, although without being differentially expressed between control and lipedema thighs." (PMID 35625899, 2022).
non-small cell lung carcinoma (4 papers, 2014 to 2025). A group of at least three distinct histological types of lung cancer, including non-small cell squamous cell carcinoma, adenocarcinoma, and large cell carcinoma. "METTL3 promotes estrogen production by enhancing CYP19A1 translation and mediates miR-196a, thereby driving non-small cell lung cancer (NSCLC) metastasis." (PMID 41256854, 2025). "The biological roles of estrogen receptor 1 (ERS1), estrogen receptor 2 (ERS2), and aromatase (CYP19A1) genes in the development of non-small cell lung cancer (NSCLC) is unclear, as is the use of their expression as a prognostic factor." (PMID 25310221, 2014).
Stroke (4 papers, 2011 to 2021). Sudden impairment of blood flow to a part of the brain due to occlusion or rupture of an artery to the brain. "Since AhR promotes apoptosis, controls ERα, and is highly expressed in brain tissue in experimental models of stroke, we hypothesize that anti-apoptotic action of DIM against OGD is mediated via inhibition of AhR/CYP1A1 and/or stimulation of ERα/CYP19A1 signaling pathways." (PMID 30778709, 2019).
adrenocortical carcinoma (3 papers, 2008 to 2022). "Indeed, 21 was able to decrease its activity in H295R adrenocortical carcinoma cells (86% aromatase inhibition at 1 μM of 21), which was in good agreement with the docking simulations performed for the complex with a human placental aromatase cytochrome P450 (CYP19A1) model." (PMID 34070457, 2021).
aromatase excess syndrome (3 papers, 2012 to 2023). Aromatase excess syndrome is a rare, genetic endocrine disease characterized by increased levels of estrogen due to elevated extraglandular aromatase activity. "Such presentation is similar to that observed in cases of aromatase excess syndrome due to rearrangements in the CYP19A1 gene." (PMID 26366315, 2015).
Coronary Artery Disease (3 papers, 2015 to 2017). "The relationship between CYP19A1 genetic polymorphisms and coronary artery disease (CAD) remains unclear." (PMID 29228596, 2017).